SMANTIS (SMARCA4 interacting SWI/SNF chromatin remodeling complex scaffold lncRNA)
Synonyms: MANTIS; ANXA4-AS; n342419
Gene: Long non-coding RNA gene on chromosome 2 (69,789,541 to 69,804,663, reverse strand). Ensembl gene ENSG00000288869.
Diseases named in the same sentence as SMANTIS in open-access papers:
SMANTIS is named in the same sentence as 6 diseases in open-access papers, as found by Europe PMC text mining. Sharing a sentence is not in itself a finding about the gene and the disease. The quoted sentences say what the papers report.
coronary artery disease (1 paper, 2024). "Additionally, it has been discovered that Dioscin, a plant-derived saponin that has been reported to exert positive effects for the treatment of coronary artery disease (CAD), functions through the induction of SMANTIS." (PMID 39273673, 2024).
SMANTIS also shares sentences with these, for which no sentence is quoted: atherosclerosis (2 papers); acute myeloid leukemia (1); endothelial dysfunction (1); glioblastoma (1); myocardial infarction (1).